TNF (tumor necrosis factor)
Diseases named in the same sentence as TNF in open-access papers (continued):
Sharing a sentence is not in itself a finding about the gene and the disease.
COVID-19 (continued). "A correlation with worse clinical outcome in COVID-19 and high levels of IL-6 and TNF alpha has previously been reported." (PMID 37614753, 2023). "Among these cytokines, levels of IL-1β, IL-6 and TNF-α were also significantly elevated in individuals with ongoing post-acute sequelae of COVID-19, and they were positively correlated with each other." (PMID 37674675, 2023). "Some proinflammatory markers that are elevated during severe COVID-19 include IL-6, IL-8, IL-1β, TNF-α, MCP-3, TGF-β, CXCL10 and IL-17, amongst others." (PMID 37153606, 2023). "Various cytokines (IFN-γ, IL-1β, IL-6, IL-2, and TNF-α) had altered levels in COVID-19, and the cytokine storms correlate with the severity and progression of COVID-19." (PMID 37565145, 2023). "Our results indicate that patients recently recovered from mild and/or severe COVID-19 show semen inflammation as evidenced by elevated seminal plasma levels of IL-1β, TNF and IFNγ with respect to control individuals." (PMID 37497433, 2023). "The activation of T cells and their ability to produce large amounts of effector cytokines (IL-2, IFNγ, and TNF) was also reflected by EVs obtained from COVID-19 patients with severe disease in the current study." (PMID 36982991, 2023). "The percentage of methylation of the TLR4 and TNF-α promoters was significantly higher in COVID-19 patients than in healthy subjects (P = 0.003 and 0.005, respectively)." (PMID 36840831, 2023). "Human neutrophils were treated with plasma–derived EVs from COVID-19 patients or HC subjects for 24 h; the supernatants were collected and the levels of IL-1β/TNF-α/IL-8 were analyzed using ELISA." (PMID 37904132, 2023). "Accumulating evidence showed that increased IL-1β/TNF-α/IL-8 in the serum of patients with COVID-19, compared to those in HC subjects." (PMID 37904132, 2023). "Among COVID-19 patients, the highest reported serum concentration of IL-1 β level was 140 pg/mL, whilst IL-6’s was 249.0 pg/mL, and TNF-α’s was 151.59 pg/mL." (PMID 37106750, 2023). "Hypertensive COVID-19 patients from both infection waves had significantly higher serum concentration of IL-6, TNF, IP-10, IL-29, IL-8, IL-12p70, IFN-α2, IFN-β, IL-10 and IFN-γ in comparison with controls." (PMID 36817433, 2023). "Patients with critical COVID-19 have been found to have higher serum levels of Gal-3, along with increased proinflammatory cytokines (IL-1β, TNF-α, IL-12) and chemokine C-C chemokine receptor type 5 (CCR5) expression in T cells." (PMID 37298569, 2023). "Among the proinflammatory cytokines, the level of TNF-α is consistently higher in severe COVID-19 patients and casualties." (PMID 37047115, 2023). "TNFα and IL-6 are reported to play key roles in cytokine storms and are likely to be responsible for the escalation in disease severity of COVID-19." (PMID 38143504, 2023). "Consistent with the pathophysiological role of TNF-α, infliximab rapidly abrogates pathological inflammatory signaling and facilitates clinical recovery in both severe and critical COVID-19." (PMID 37109231, 2023). "The levels of IFN-γ, IL-1Ra, IL-6, and MCP-1 were elevated in male patients with severe COVID-19, while those of TNF-α were high in COVID-19 female patients." (PMID 37896963, 2023). "In the present study, KEGG analysis of 212 DEGs of GSE36854 and GSE21001 for MPXV infection showed its involvement in COVID-19, cytokine-cytokine receptor interaction, and TNF signaling." (PMID 37006463, 2023). "KEGG signaling pathway analysis indicated that bitter almond-licorice was involved in the IL-17 signaling pathway, TNF signaling pathway and Th17 cell differentiation in the treatment of COVID-19, all of which were closely related to the inflammation process." (PMID 38018195, 2023). "This provides robust evidence for adopting TNF-α as a more promising predictor for the prognosis of severe and life-threatening forms of COVID-19." (PMID 37047115, 2023).
COVID-19 (continued). "In bacterial sepsis, MDSC expansion, IFN-γ production, and TNF-α production reduced over time from admission, but in COVID-19 these responses accelerated over time, despite initial lesser physiological derangement." (PMID 37545508, 2023). "Heatmap constructs further illustrated that the major increase in serum soluble mediators observed in pregnant women with convalescent COVID-19 occurred in pro-inflammatory cytokines, namely IL-6, TNF-α, IL-12, IFN-γ and IL-17." (PMID 37122732, 2023). "Placental expressions of caspase-3, caspase-1, and TNF-alpha were significantly high in pregnancies complicated by both COVID-19 and preeclampsia, suggesting highly morbid placental damage with unfavorable perinatal outcomes." (PMID 37362630, 2023). "Serum levels of IL-23, IL-10, and TNF-α were significantly higher in COVID-19 patients with critical cases compared to mild and severe cases, and correlated positively with CRP level." (PMID 37283736, 2023). "A high level of TNF-α in the serum and/or plasma of patients with COVID-19 reported in previous studies is consistent with the findings of the present study indicating abnormally activated host immune cells." (PMID 37034572, 2023). "Amongst the proinflammatory cytokines found in COVID-19 patients and casualties, the expression of TNF-α and IL-6 outdoes that of their counterparts." (PMID 37047115, 2023). "We showed a largely increased TNF-α concentration in COVID-19 female patients at diagnosis that was normalized in post-COVID-19 patients." (PMID 37896963, 2023). "To date, we have not identified A3A inducers (except for the combination of IFN-ß and TNF-α) that are truly active in COVID-19 patients in vivo." (PMID 36610792, 2023). "The key cytokines produced by the immune system in patients with severe COVID-19 are interleukins (IL-1, IL-2, and IL-6), TNF-α, and interferons (IFNs)." (PMID 37240319, 2023). "Zn can be used as a supplement for COVID-19 prevention as it helps in reducing the occurrence of respiratory infection due to its antiviral and anti-inflammatory properties by inhibiting TNF-α." (PMID 38235136, 2023). "In the present study, we reported the clinical manifestations and inflammatory markers including cytokines (IL-6, IL-1β, and TNF-α) in 35 Turkish children with PCR-positive COVID-19." (PMID 37034144, 2023). "Another study has confirmed these data showing that serum levels of several pro-inflammatory mediators such as IL-6, CXCL8 and TNFα and also serum NETs levels are increased in COVID-19 patients (n = 27), compared to healthy subjects (n = 12)." (PMID 36941580, 2023). "On the other hand, eight out of ten anti-COVID-19 core targets (TNF, EGFR, CASP3, AKT1, MAPK1, MAPK3, mTOR, and IL-6) followed the human cytomegalovirus infection." (PMID 36817449, 2023). "Serum concentrations of proinflammatory cytokines and chemokines—including IFN-γ, TNF-α, IP-10, G-CSF, IL-2, IL-6, IL-8, IL-9, IL-10, and IL-17—were increased in patients with severe COVID-19 and strongly correlated with disease outcome." (PMID 36776881, 2023). "Anti-inflammatory agents such as corticosteroids, NSAIDs, monoclonal antibodies against as IL-6 (Tocilizumab), IL-1 (Canakinumab), and TNF-α (Adalimumab and Golimumab), and Interferon-based immunotherapy can be applied to treat COVID-19 patients." (PMID 37365605, 2023). "IL-1α, IL-1β, IL-8, IFN-γ, VEGF-A, and TNF-α had returned to normal levels 6 months after recovery, but IL-1Rα was still elevated in COVID-19 convalescents, compared to healthy controls." (PMID 37077911, 2023). "Monoclonal antibodies as well as anti-tumor necrosis factor are considered promising treatments for COVID-19." (PMID 37081046, 2023). "Ratios of serum levels of IL-10 and Gal-3 with IL-1β, TNF-α and IL-12 in all stages of COVID-19 were made." (PMID 36702907, 2023).
COVID-19 (continued). "C-reactive protein (CRP), Tumor Necrosis Factor-α (TNF- α), interleukin-6 (IL-6), IL-8, CXCL10, peripheral inflammation biomarkers linked to COVID-19 severity, also predict sequelae, as well as Type I and Type III interferons (IFN)." (PMID 38235145, 2023). "The overexpression of CRP, ferritin, LDH, TNF-α, IL-1β, IL-6, IL-2, IFN-γ, and vascular endothelial growth factor (VEGF) can be associated with COVID-19 severity." (PMID 37654571, 2023). "TNFα, IL1β and IL6 are known to be associated with post-acute sequelae of COVID-19 and used as biomarkers of SARS-CoV-2 infection in previous study." (PMID 36697403, 2023). "Concomitantly, the production of TNF-α before stimulation is significantly increased in patients with severe COVID-19 compared to healthy donors (p=0.0001) and patients with moderate disease (p<0.0001)." (PMID 37342247, 2023). "Multiple inflammatory factors are significantly increased in COVID-19 patients, such as interleukin-6 (IL-6), tumor necrosis factor-α (TNF-α), and C-reactive protein (CRP)." (PMID 37583958, 2023). "Although the p62 blood levels in COVID-19 patients at diagnosis were decreased, they were positively correlated with the amounts of TNF, IL-17, IL-10, and IL-33." (PMID 37174682, 2023). "Studies have shown that TNFα and IL-6 are highly elevated in the blood of patients with severe COVID-19." (PMID 36482706, 2023). "The current study showed that patients under CHD hospitalized for moderate COVID-19 have increased circulating levels of TNFα, IFNγ and PDGF-A, decreased CD14-lymphocytes, decreased CD19-lymphocytes and decreased expression of HLA-DR on CD14-monocytes." (PMID 37674148, 2023). "Of note, at 10 μM, MB-905 also diminished SARS-CoV-2-induced TNF and IL-6 levels, a desired feature for antivirals against COVID-19." (PMID 36639383, 2023). "The majority of studies have reported that proinflammatory cytokines, such as interleukin (IL)-6, tumor necrosis factor α (TNFα), and IL-1β, are related to COVID-19 pathogenesis." (PMID 37515185, 2023). "e Silva and colleagues propose that tumor necrosis factor-α (TNF-α) and IL-6 are the two major cytokines upregulated in COVID-19 that directly affect brain physiology." (PMID 37415915, 2023). "Recent evidence shows that, in COVID-19 infection, there is an increase in the plasma cytokine levels, especially IL-6, TNF alpha, and chemokines, which have a positive correlation with COVID-19 severity." (PMID 37181975, 2023). "The marked increase in COVID-19 disease severity is a result of neutrophil migration and G-CSF, TNF-a, IL-1b and IL-6 activation." (PMID 37091818, 2023). "We analysed the serial MPO, ADA, CCL22, TNFα, and IL-6 mRNA expression in nasopharyngeal specimens of 154 COVID-19 and 163 control hospitalized patients in the fifth wave of COVID-19 in Hong Kong." (PMID 36482706, 2023). "This recent study has shown that Preeclampsia with COVID-19 had the worst necrosis condition in the placenta compared with COVID-19 only or preeclampsia only, which is demonstrated by TNF-alpha expression." (PMID 37362630, 2023). "Other research teams have reported that a significant increase in IL-10 and TNF-α is observed in more severe cases of patients with COVID-19." (PMID 37759873, 2023). "Various inflammatory cytokines, such as interleukin IL-6, IFN-γ, and tumor necrosis factor-α, are elevated in patients with severe COVID-19." (PMID 36810114, 2023). "In fact, we detected semen inflammation in patients recently recovered from mild and/or severe COVID-19 as shown by increased levels of IL-1β, TNF and IFNγ in seminal plasma." (PMID 37497433, 2023). "In this study, we demonstrated an increase in IL-10, IL-23 and TNF-α in serum samples of COVID-19 patients during mild disease and continue to increase in the severe stage and reach the highest level in the critical phase of the disease." (PMID 37283736, 2023).
COVID-19 (continued). "TNF demonstrated the highest expression, which was 29.35-fold higher in the neonates of mothers with COVID-19 than in the control group." (PMID 36979888, 2023). "KEGG analysis of 212 DEGs of GSE36854 and GSE21001 for monkeypox infection showed involvement of monkeypox in COVID-19, cytokine-cytokine receptor interaction, inflammatory bowel disease, atherosclerosis, TNF signaling, and T cell receptor signaling." (PMID 37006463, 2023). "The cytokine storm of COVID-19 patients (with an elevation of IL-1β, IL-6 and TNF-α) has been related to the increase of eicosanoids including AA and its metabolites." (PMID 36984782, 2023). "During COVID-19 progression, abnormal levels of IL-1β, TNF-α, IL-2, IL-7, IL-12, macrophage colony-stimulating factor (M-CSF), granulocyte colony-stimulating factor (G-CSF), and others can be detected in patient’s blood." (PMID 36702907, 2023). "We treated purified total monocytes from uninfected and convalescent COVID-19 subjects with LPS and measured TNF-α and IL-6 production by ELISA." (PMID 38250080, 2023). "Our findings confirm a defined cytokine signature in severe COVID-19 (with elevated IL-2, IL-6, TNFα, IL-1β and IL-10), and add further evidence to the role of IP-10, G-CSF and IL-33 in the cytokine milieu associated with severe COVID-19." (PMID 37063871, 2023). "The study showed that in both groups of patients, with OA and convalescent COVID-19, there was an increase in the plasma level of IL-1β and a decrease in TNF-α and NF-κB levels when compared to healthy controls." (PMID 37484856, 2023). "Chen and colleagues reported that in severe cases of COVID-19, there were higher levels of IL-6 and TNF-α than in mild cases." (PMID 37363608, 2023). "Even after the COVID-19 vaccine booster dose, the TNFα inhibitors selectively decreased the humoral immune response compared to patients on other treatment regimens." (PMID 36992175, 2023). "After receiving the AstraZeneca-Oxford COVID-19 vaccine, an increase in the production of tumor necrosis factor (TNF)-α and interferon (IFN)-γ by CD4+ T cells was observed." (PMID 37305120, 2023). "In this study, the downregulation of miR-146b was associated with an increased expression of pro-inflammatory cytokines, such as IL-6 and TNF-α, in severe COVID-19 patients." (PMID 38136554, 2023). "Our analysis did not reveal any statistically significant difference in CD147, miR-492, and TNF expression levels among the three genotypes of rs8259T>A in patients with COVID-19." (PMID 37630479, 2023). "The levels of all analyzed interleukins, including TNF, IL-6, IL-1B, IL-8, IL-10, and IL-12p70, were significantly higher in the COVID-19 group compared to the control group." (PMID 37373613, 2023). "Nevertheless, severe COVID-19 patients exhibit high levels of TNF-α, contributing to lung damage and a poor prognosis." (PMID 37376569, 2023). "Anti-TNF-α medication has lately been proposed as a strategy for lowering inflammation in COVID-19 patients after IL-6 blocking showed little efficacy." (PMID 37124230, 2023). "In patients with COVID-19, RDW has been shown to be correlated with IL-6 levels, as well as TNF-α, likely due to IL-6 induction of hepcidin expression, while TNF-α has been linked to erythropoietin resistance." (PMID 36829793, 2023). "Regarding COVID-19, eight studies showed increased IL-1β, IL-6, and TNF-α in these cases compared to the controls, five studies showed elevated IL-6 alone, and one study indicated higher TNF-α alone." (PMID 37106750, 2023). "Conclusively, to precisely propose the use of TNF-α in the prognosis and treatment of COVID-19, further studies and rigorous empirical investigation are warranted to help people affected by COVID-19 in the near future." (PMID 37047115, 2023). "Inhibitors of TNF-α, another inflammatory cytokine that plays an important role in the severity of the disease, have also been suggested as a therapeutic approach for COVID-19." (PMID 36936055, 2023).
COVID-19 (continued). "Although previous studies have shown that patients with COVID-19 residing in high-altitude tend to have higher levels of inflammatory cytokines, particularly IL-6, IL-10 and TNF-α." (PMID 37264338, 2023). "Individuals affected by COVID-19 who need treatment in intensive care units usually have high levels of interleukin (IL)-2, IL-7, IL-10, tumor necrosis factor α (TNF-α), and other pro-inflammatory and also anti-inflammatory cytokines." (PMID 37408184, 2023). "Observational studies showed elevated levels of different cytokines in COVID-19 patients, such as TNFα, IL-1β, IL-6, IL-8, IL-10, and IL-17." (PMID 36983830, 2023). "Other reports have shown Withaferin A, a bioactive steroidal lactone derived from WS, to be anti-inflammatory by reducing the levels of inflammatory cytokines such as IL-6 and TNFα which is desirable in COVID-19 patients to alleviate pulmonary pathology." (PMID 36960064, 2023). "In COVID-19 patients, plasma levels of pro-inflammatory cytokines, including interleukin (IL)-1α, IL-1β, and tumor necrosis factor α (TNF-α), are elevated, compared to healthy adults." (PMID 36671034, 2023). "Regarding TNF-α, a significantly increased tissue expression was observed in the COVID-19 group compared to the CONTROL group (p = 0.0006)." (PMID 36992415, 2023). "A previous study showed that the plasma cytokine levels such as IL-6, IL-1β, IL-10, IL-21, and TNF-α were significantly higher in asymptomatic group compared to the controls, indicating an increased inflammation in asymptomatic COVID-19 patients." (PMID 37869674, 2023). "In the peripheral blood of patients with more severe stages of COVID-19 we detected significantly increased percentages of CD56− CD3+TNF-α+T cells and CD56− CD3+Gal-3+T cells and increased expression of CCR5 in PBMCs." (PMID 36702907, 2023). "The cytokine profile of the inflammatory cascade in SARS-CoV-2 was well defined, with concentrations of TNF-α, IL-6 and IL-10 distinctly mediating the cytokine storm and clearly differentiating mild from severe cases of COVID-19." (PMID 37759873, 2023). "In our study, we observed a significant positive correlation between increased serum levels of IL-10, IL-23 and TNF-α in COVID-19 patients." (PMID 37283736, 2023). "In summary, we were able to establish an accurate model to early predict post COVID-19 symptomatology based on IL-1β, TNF-α and MIP-1α levels one month after the onset of the acute SARS-CoV-2 infection." (PMID 37894054, 2023). "In summary, the present study demonstrates the increase in nasopharyngeal MPO, ADA, CCL22, TNFα, and IL-6 mRNA expression in COVID-19 patients." (PMID 36482706, 2023). "To determine the pro-inflammatory effects of S1 spike protein on BEAS-2B and A549 cells, we measured the levels of IL-1β, TNF-α, IL-6, and IL-8, crucial inflammatory cytokines in COVID-19." (PMID 37834316, 2023). "Recent studies have shown that COVID-19 patients were more rarely treated in hospitals due to taking anti-TNF drugs for other conditions." (PMID 37033914, 2023). "TNF-α and TGF-β, which are elevated in COVID-19 infection and COVID-19 vaccine-associated myocarditis, are both involved in cardiac remodeling and fibrosis." (PMID 36851240, 2023). "When COVID-19 progresses to severe illness, higher serum levels of IL-6, CXCL8, TNF-α, and IL-1β are associated with hyperinflammatory and hyper-coagulable conditions." (PMID 37908356, 2023). "As with IFN-γ, TNF-α is known to be a critical component of the immune response against both tuberculosis and COVID-19." (PMID 38004820, 2023). "The highly expressed cytokines in COVID-19 patients included IL-10, IL-6, IL-7, TNF-α, IFN-α, CCL2, and CCL4, but only incubation monocytes with IL-10 downregulated HLA-DR expression." (PMID 36834656, 2023). "MTX, retinoids, IL-17 inhibitors, and IL-12/23 inhibitors; Avoid TNF-α inhibitors and cyclosporine in COVID-19 patients." (PMID 38029150, 2023).